IRS1 (insulin receptor substrate 1)
Diseases named in the same sentence as IRS1 in open-access papers (continued):
Sharing a sentence is not in itself a finding about the gene and the disease.
Insulin resistance (continued). "Besides peripheral insulin resistance, this alteration may be present in the brain accompanied by IGF1 resistance, and IRS-1 and IRS-2 dysfunction, potentially triggered by Aβ oligomers and cognitive decline." (PMID 25346723, 2014). "Thus, chronic activation of mTORC1/S6K induces insulin resistance through a negative feedback loop involving the serine phosphorylation and the degradation of IRS-1." (PMID 23272222, 2012). "In aortic endothelial cells, ANG II can stimulate mTOR and p70S6K activation that phosphorylates IRS1 and inhibits endothelial nitric oxide synthase that not only may contribute to insulin resistance but also to vasoconstriction and hypertension." (PMID 22545721, 2012). "Furthermore, we showed in this study that p/CIP and SRC-1 suppress IRS1 levels to control insulin resistance in different obesity models, which has not been reported before." (PMID 22859932, 2012). "It was also reported that fetuin-A could inhibit insulin receptor tyrosine kinase activity through blocking the autophosphorylation of tyrosine kinase and insulin receptor substrate-1(IRS-1), and induced a lower-grade inflammation, which resulted in insulin resistance." (PMID 21556362, 2011). "In addition, results show that 15 Hz EA on the bilateral Zusanli acupoints may improve insulin resistance by decreasing the plasma FFA levels and recovering the expression of insulin signal proteins (IRS1 and GLUT4), which enhances insulin activity." (PMID 19646276, 2009). "Although much of the current literature suggests that insulin resistance is an aetiological factor in AD, we have recently demonstrated that mice lacking Irs1 have increased lifespan and reduced age-related pathology and deletion of Irs2 in the mouse brain increases longevity." (PMID 19523444, 2009). "IRS-1, principal substrate for insulin and insulin like growth factor (IGF-1) receptors is involved in glucose clearance and is an attractive candidate gene to harbor genetic variation that might influence insulin resistance and obesity." (PMID 20300294, 2008). "Finally, a prolonged exposure to insulin (a typical conditionin hyperinsulinemic patients) may result in a degradation of IRS protein.All together, these data support IRS-1 and IRS-2 as crucial players in thedevelopment of insulin resistance." (PMID 18604303, 2008). "However, we have not assayed the levels of various phosphorylated forms of IRS1, and in addition, there was no reduction in Akt and p-Akt levels, which did not confirm the development of insulin resistance in the examined brain structures in animals prenatally exposed to DEX." (PMID 36674678, 2023). "Thus, impaired IRS-1 level and tyrosine and/or serine-632 IRS-1 phosphorylation in the gastrocnemius muscle of OZRs may be an important mechanism contributing to the pathogenesis of insulin resistance in obesity and type 2 diabetes." (PMID 36547071, 2022). "Liver-specific Irs1-knockout mice (LIrs1KO) failed to exhibit insulin resistance during fasting, but showed insulin resistance after refeeding; conversely, liver-specific Irs2-knockout (LIrs2KO) mice exhibited insulin resistance during fasting, but not after refeeding." (PMID 33923817, 2021). "Notably, hepatic levels of insulin receptor substrate 1 (IRS-1), an important mediator in insulin resistance, were significantly decreased in the WD+GWI group when compared to the Chow+GWI group, suggesting that Western diet feeding worsened insulin resistance." (PMID 32927823, 2020). "Interestingly, in vivo studies also confirmed kaempferol ameliorates insulin resistance through inhibiting pro-inflammatory responses, particularly by reducing NF-κβ, TNF-α, and IL-6 levels, and restoring insulin resistance by inhibiting phosphorylation of IRS-1." (PMID 32694996, 2020). "Insulin resistance in the absence of hyperglycemia found in the HL group in this study may have occurred due to the ability of IRS-2 to partially compensate for the absence of IRS-1." (PMID 32881885, 2020).
Insulin resistance (continued). "Our study further demonstrated that RES administration could reverse insulin resistance, decrease CCR2 expression in SAT and VAT, and reduce inflammation and macrophage infiltration of SAT and VAT, thus increasing insulin signaling molecules (such as IRS-1, GLUT4 and pAkt) in HFD-induced obese mice." (PMID 29967759, 2018). "Bovine α-LAH also suppresses IRS-1 phosphorylation, enhances Akt phosphorylation, and inhibits the activation of IKK and MAPK signaling pathways in the adipose tissues of HFD-fed C57BL/6J mice, which may contribute to its protective effects against insulin resistance and inflammation." (PMID 29473848, 2018). "However, 2.70% dietary arginine level results in high plasma glucose, which could lead to negative feedback of insulin resistance, including inhibition of IRS-1 mRNA levels and activation of gluconeogenesis-related gene expression." (PMID 28801592, 2017). "Thus, the reduced IRS‐1 protein levels observed in skeletal muscle following polytrauma may not be a major contributor to the polytrauma‐specific insulin resistance observed at 24 h." (PMID 26818585, 2016). "In insulin resistance, diabetes, and overt diabetic nephropathy, IRS2-dependent stimulation of sodium transport by insulin in the PT is preserved and this may induce sodium retention, whereas IRS1-dependent suppression of gluconeogenesis is attenuated and might induce hyperglycemia." (PMID 27247938, 2016). "While the effect of insulin sensitivity on lifespan is complex – some insulin-resistant mice, such as mice lacking IRS1, are long lived – many long-lived mouse models have increased insulin sensitivity, and diet-induced insulin resistance shortens mammalian lifespan." (PMID 25059582, 2014). "Mice lacking IRF3 showed reduced insulin receptor substrate 1 (IRS1) and protein kinase B (AKT) phosphorylation in the liver, worsening insulin resistance." (PMID 39669992, 2024). "In male and ovariectomized (OVX) female mice, FoxO1 was found to be required for the improvement of estrogen on insulin resistance, which is through activation of ERα- PI3K-Akt-FoxO1 signaling, which is independent of IRS1 and IRS2." (PMID 36942499, 2023). "Insulin resistance in the muscle of non-obese normoglycemic subjects is related to JNK activation connected to increased intramyocellular lipids and IRS-1 serine phosphorylation." (PMID 35884769, 2022). "have used the haploinsufficient insulin receptor substrate-1 (IRS-1) mice to model maternal obesity and maternal insulin resistance during pregnancy without the need of diet-induction." (PMID 36189369, 2022). "In our study, we identified 17 upregulated genes (out of 20 total in this pathway), including IRS1 and tyrosine-protein phosphatase non-receptor type 11 (SHP2), suggesting increased glucose uptake and decreased insulin resistance." (PMID 32655508, 2020). "In contrast, systemic insulin resistance was observed in cases of APPL1-/- mice, and insulin stimulation did not increase the expression level of IRS1/2." (PMID 32059381, 2020). "By contrast, there was little or no increase in the ratio of pIR/IR or pIRS-1/IRS-1 in HFD-fed mice following insulin injection, indicating central insulin resistance." (PMID 29910467, 2018). "Mice lacking the insulin receptor substrate 1 (IRS1−/−) but not IRS2 (IRS2−/−) are long-lived, but strangely have lifelong insulin resistance, while being also resistant against age-sensitive markers." (PMID 28768896, 2017). "These increases in O-GlcNAc levels do not induce insulin resistance functionally, measured using a 2-deoxyglucose (2-DOG) uptake assay, or at the molecular level, determined by evaluating levels of phosphorylated IRS-1 and Akt." (PMID 20851343, 2010). "This study measures the IRS1 and GLUT4 levels of EA and non-EA samples for both steroid background and saline groups to evaluate the possible effects of EA on insulin resistance." (PMID 19646276, 2009).
Insulin resistance (continued). "PKCα phosphorylates insulin receptor substrate 1 (IRS‐1), inhibits insulin receptor signaling in negative feedback, reduces glucose transporter type 4 (GLUT4) membrane translocation and glucose uptake, and is involved in insulin resistance." (PMID 41244006, 2025). "In contrast, IRS-1 phosphorylated at Ser312 and c-Jun N-terminal protein kinase activation (p-JNK) are considered negative substrates in somatic cells because they induce insulin resistance and apoptotic alterations." (PMID 37298039, 2023). "In our study, the suppression of hypothalamic PTEN in HFD-fed rats reversed insulin resistance without exerting effects on food intake, indicating that the HFD-induced blockage of hypothalamic insulin signals, such as IRS-1 serine phosphorylation, exist upstream from PI 3-kinase." (PMID 30875909, 2019). "Other studies also suggest that muscle IRS1, but not IRS2, is reduced in insulin resistance." (PMID 27247938, 2016).
Obesity (268 papers, 2004 to 2026). Accumulation of substantial excess body fat. "The findings indicate that PF extract can prevent skeletal muscle loss and IR in obesity by modulating oxidative stress, inflammation, and activating IRS-1/PI3K/AKT signaling pathway." (PMID 42083443, 2026). "This study highlights the potential of early-life epigenetic marks, such as those identified in IRS1, as predictive tools in identifying children at a higher risk of developing obesity and related metabolic conditions." (PMID 40243885, 2025). "mTOR regulates insulin signaling via IRS1 in metabolic tissues and is implicated in diseases like type 2 diabetes, obesity, and cancer." (PMID 40243885, 2025). "Further analysis of IRS1 methylation and expression in the placenta and blood at 6 years revealed significant associations with metabolic risk and obesity-related parameters at this age." (PMID 40243885, 2025). "Of note, the gene Irs1 was found to be differentially expressed in placentas in association with paternal obesity, validating our previous findings in the initial characterization of the model." (PMID 39612469, 2024). "Obesity in PCOS has been linked to increased serine phosphorylation of insulin receptor substrate-1 (IRS-1), which further disrupts insulin signaling." (PMID 39665024, 2024). "Obesity-associated inflammation can impair insulin signaling through serine phosphorylation of insulin receptor substrate-1 (IRS-1) and inhibiting phosphatidylinositol 3-kinase (PI3K)/protein kinase B (PKB) signaling, resulting in impaired glucose uptake." (PMID 37424869, 2023). "Genes associated with increased obesity are frequently associated with disease risk factors, such as the gene polymorphism of insulin receptor substrate 1 (IRS1), which is linked to the risk of metabolic diseases." (PMID 35910571, 2022). "This study aimed to evaluate changes of the glycemic profile and IR in T2DM with comorbid obesity and chronic pancreatitis (CP) considering the allele status of the IRS1 gene (rs2943640)." (PMID 35221617, 2021). "A strength of our study is that it is the first investigation of IRS-1 gene polymorphisms among T2DM patients with comorbid obesity and CP in Ukrainian population." (PMID 35221617, 2021). "A short-term intervention with CAD induced a higher relative abundance of L. Lactis, B. pseudolongum, and higher mRNA levels of genes AdipoQ and Irs1 involved in obesity associated pathways compared with CHPD." (PMID 31708891, 2019). "The CAD also upregulated gene expression involved in obesity associated pathways (e.g., Adipoq and Irs1) in cecal tissue of rats." (PMID 31708891, 2019). "Third, in contrast to IRS1/2 deficient strains, mice heterozygous for IRS1 showed hyperinsulinemia and glucose intolerance only in the presence of obesity." (PMID 26946982, 2016). "The activation of JNK and subsequent serine phosphorylation of insulin receptor substrate 1 (IRS1) in adipose tissue is postulated to be a key nexus by which a number of obesity-associated stimuli can directly impair insulin-dependent signaling." (PMID 25375135, 2014). "Studies of insulin receptor substrate‐1 (IRS‐1) phosphorylation in mice have demonstrated a status of chronic low‐grade inflammation associated with adipose tissue cytokine production in obesity." (PMID 25472611, 2014). "Obesity in the domestic cat has been linked to decreased IRS-1 and IRS-2 expression levels in liver and skeletal muscle." (PMID 24312255, 2013). "In the present study, we aimed to find out the association of demographic, hormonal and genetic factors like β2-AR (-47 and -20 T/C) and IRS-1 Gly972Arg gene polymorphisms with obesity in north Indian population." (PMID 20300294, 2008). "In this study, we investigated 2 genetic variants of the β2 AR gene and 1 genetic variant of IRS-1 gene as candidates to predispose obesity." (PMID 20300294, 2008).
Obesity (continued). "(iv) Decrease in the association of PI3K with phosphorylated IRS-1 and subsequent activation appears to be a characteristic abnormality in type 2 diabetes and obesity." (PMID 15291972, 2004). "Indeed, hypothalamic iNOS overexpression triggers brain IR and obesity through mechanisms involving the S-nitrosylation of insulin signalling-associated molecules such as IRS-1 and AKT." (PMID 40243721, 2025). "We propose that placental IRS1 methylation may play a role regulating obesity and metabolic risk parameters and could serve as an early biomarker for metabolic risk." (PMID 40243885, 2025). "Our results suggest that IRS1 may serve as a potential biomarker for the prediction of obesity and metabolic risk in children." (PMID 40243885, 2025). "Furthermore, IRS-1 expression was decreased in type 2 diabetes and obesity subjects, and low IRS-1 expression causes a decrease in insulin-stimulated glucose uptake." (PMID 37711887, 2023). "AP-2β can target multiple features of obesity and T2D centrally and peripherally by modulating key-obesity linked genes such as IRS-1, GLUT4, adipocytokines related genes, as well as catecholaminergic and serotonergic genes involved in reward, consummatory behaviour and insulin resistance." (PMID 36076256, 2022). "One study, which investigated disease-associated SNPs by applying an eQTL analysis, showed that several SNPs regulated gene expression levels in a tissue-specific manner, for example, the IRS1 gene in adipose tissue and influenced the risk of obesity and type 2 diabetes." (PMID 35276838, 2022). "Irs2 is a paralog of Irs1 encoding insulin receptor substrate-2, which is similarly phosphorylated by insulin receptor kinase and linked to diabetes, but additionally has haplotypes associated with severe obesity." (PMID 33330474, 2020). "Interestingly, the core variable species L. lactis was positively correlated with those genes such as AdipoQ, Irs1, Cd 36, and Pde3b involved in obesity associated pathways." (PMID 31708891, 2019). "Obesity has been linked with increased endoplasmic reticulum stress, which leads to suppression of insulin receptor signaling via hyperactivation of Jnk and subsequent serine phosphorylation of IRS-1." (PMID 16961925, 2006). "Western blot analysis revealed that, compared with controls, the protein expression levels of GLUT4 and p-IRS1 were markedly decreased in the obesity group (P < 0.0001), whereas HIF-1α and TNF-α protein levels were significantly increased (P < 0.0001)." (PMID 41505418, 2026). "In summary, treatment with pea peptides can effectively reduce blood glucose levels and glucose tolerance in mice with high-fat-diet-induced obesity, regulating glucose metabolism through the IRS-1/PI3K/Akt signaling pathway." (PMID 40941124, 2025). "An EWAS in blood from children with obesity and children of normal weight found that “IRS1 target genes” were among the top enriched pathways in the identified CpGs." (PMID 40243885, 2025). "Recent studies have also shown sex differences in subcutaneous adipose tissue IRS1 mRNA expression in adults with obesity." (PMID 40243885, 2025). "However, we did observe an association between IRS1 methylation and/or expression and children’s metabolic parameters at two time points (placenta at birth and leukocytes at 6 years), highlighting the potential significance of this gene in obesity development across different life stages." (PMID 40243885, 2025). "In obesity, elevated FFAs interfere with insulin signaling by impairing the tyrosine phosphorylation of IRS-1, which contributes to the development of IR, hepatic lipid accumulation, and oxidative stress." (PMID 40777174, 2025). "The IRS1 and its pathway have a broad spectrum of biological functions, so any defects in them can lead to metabolic disorders such as IR and obesity that play a key role in NAFLD pathogenesis." (PMID 39420901, 2024).